IL17A (interleukin 17A)
Diseases named in the same sentence as IL17A in open-access papers (continued):
Sharing a sentence is not in itself a finding about the gene and the disease.
Hypertension (continued). "Injection of activated Th17 lymphocytes isolated from fructose-fed SS rats induced hypertension via increase of serum IL-17A only in recipient SS rats." (PMID 32179549, 2020). "In SS rats, it induces hypertension by increasing the population of CD4+IL-17A+ (Th17) cells, which secrete pro-inflammatory cytokine IL-17A." (PMID 32179549, 2020). "Of interest, IL-17A contributes to the pathogenesis of several cardiovascular disorders, mainly hypertension, atherosclerosis, and ischemic heart disease." (PMID 32987705, 2020). "During Ang II–dependent hypertension, IL-17A together with IFN-γ interferes with the pressure natriuretic decrease in proximal tubule sodium transporters." (PMID 31321561, 2019). "Our study shows that IL-17A increases blood pressure, and therefore, additional studies are needed to further address the relation between IL-17A, hypertension, and renal inflammation." (PMID 31572188, 2019). "Vascular inflammation in AngII-induced hypertension and vascular dysfunction was described to be IL-17A-dependent." (PMID 31396305, 2019). "All these data support the role of IL-17A in the regulation of inflammatory process in pathological conditions, including renal diseases and hypertension." (PMID 31572188, 2019). "The animals were shown to develop vascular collagen deposition, aortic stiffening, renal dysfunction, and hypertension with age and presented a significant overproduction of IL-17A and IFN-γ." (PMID 31396305, 2019). "Experimental data support a role for Th17 cells and its effector cytokine IL-17A in the pathogenesis of hypertension." (PMID 31572188, 2019). "Interleukin 17A (IL-17A), the effector cytokine of Th17 cells, has emerged as a promising therapeutic target in immune and chronic inflammatory diseases, including hypertension and chronic kidney disease." (PMID 31572188, 2019). "In summary, the present data support a role of IL-17A in kidney inflammation that highlights a potential contribution to regulation of hypertension." (PMID 31572188, 2019). "Experimental and clinical studies suggest that interleukin 17A (IL-17A) is a promising therapeutic target in immune and chronic inflammatory diseases, including hypertension and kidney disease." (PMID 31572188, 2019). "The intention of our study was to analyze the impact of T cell-derived IL-17A on hypertension, vascular function, and inflammation." (PMID 31396305, 2019). "In Ang II–dependent hypertension, there is an imbalance between Th17/Treg in the spleen and in renal/cardiac infiltrating lymphocytes resulting in increased expressions of IL-17A, IL-23, and TNF-α, and decreased expression of IL-10." (PMID 31321561, 2019). "In vivo study using an experimental model of Ang II‐dependent hypertension confirmed that PGG also effectively inhibited the production of IL‐17A by CD4+ and CD3+CD4−CD8− T‐cell subsets." (PMID 30658013, 2019). "The neutrophil recruiting cytokine Interleukin-17A (IL-17A) is a key component in vascular dysfunction and arterial hypertension." (PMID 31396305, 2019). "One week of IL-17A infusion induced hypertension in mice, and this effect was attributed to the upregulation of Rho-A, a redox-related protein." (PMID 31396305, 2019). "IL-17A and IFN-γ have been implicated in the genesis and maintenance of hypertension due in part to their direct effect in causing endothelial dysfunction and renal damage." (PMID 31165257, 2019). "Especially, CD4+ T cells of humans with hypertension produced higher amounts of IL-17A than normotensive controls." (PMID 31321561, 2019). "The production of cytokines like IL-6, IL-23, and IL-1β can also skew T cells produce IL-17A, which we have previously shown to be involved in hypertension." (PMID 29800237, 2018). "Therefore, targeting IL-17A is beneficial not only for the treatment of hypertension, but also for the treatment of complications such as heart failure and stroke." (PMID 40028265, 2025).
Hypertension (continued). "There is limited information on the mechanism underlying the association between IL-17A and hypertension, and there are no comprehensive reviews of the effects of IL-17A on different systems in the pressor response." (PMID 40028265, 2025). "The current study suggests that IL-17A may play an important role in salt-sensitive hypertension, and remains to be studied in other types of hypertension." (PMID 40028265, 2025). "Because T-cells producing IL-17A were increased in hypertensive patients compared to normotensive ones, it is apparent that IL-17A is associated with hypertension development; however, its clinical significance is not yet clear." (PMID 38256155, 2024). "Th17 cells, a subset of CD4+ T helper cells, produce IL-17A, which is essential for hypertension." (PMID 38673987, 2024). "Increased levels of IL-17A in circulation have been shown to result in the remodeling of small mesenteric arteries and increased arterial stiffness in mice, and these changes were considered to contribute to high blood pressure." (PMID 38256155, 2024). "However, the possible role that IL-17A plays in linking hypertension with neurodegenerative diseases remains to be established." (PMID 36835372, 2023). "Hypertension induces dendritic cells (DCs) to produce reactive oxygen species (ROS), which in turn stimulates DCs to produce IL-1β, IL-6, and IL-23, thereby promoting the polarization of T cells and producing IL-17A." (PMID 36891527, 2023). "Furthermore, mice depleted of T cells or interleukin-17A (IL-17A) were protected from the development of endothelial dysfunction and hypertension." (PMID 36620210, 2022). "Previous research has shown that gut microbiota dysbiosis could promote T helper 17 (TH17) cell activation and stimulate the production of IL-6, IFN-γ, and IL-17A, resulting in hypertension." (PMID 35887270, 2022). "Th1 and Th17 cells release pro-inflammatory cytokines, such as IFN-γ, TNF-α, and IL-17a, which are prominent pathogens in hypertension models while Treg cell inhibits Ang II-induced hypertension by releasing anti-inflammatory cytokines, which mainly include IL-10 and TGF-β." (PMID 36457803, 2022). "These IsoLG-containing immune cells infiltrate the perivascular space and kidneys and secrete pro-inflammatory cytokines including IL-1β and IL-6 from the APCs and IFN-γ and IL-17A from the T cells, resulting in vascular and kidney dysfunction and ensuing hypertension." (PMID 36620210, 2022). "The IL-17A/IL-17RA axis in the brain may represent a novel therapeutic target for cardiovascular diseases such as HF and hypertension." (PMID 36312009, 2022). "Plasma levels of IL-17A are increased in humans with hypertension." (PMID 35360231, 2022). "IL-17A that is mostly produced by activated Th17 cells is a key factor for proinflammatory responses that induce systemic endothelial dysfunction, vascular oxidative stress, and arterial hypertension." (PMID 33688497, 2021). "Therefore, early elevated levels of the proinflammatory IL-17A produced by Th17 cells are important in the development of spontaneous hypertension in SHR." (PMID 33688497, 2021). "Moreover, hypertensive patients have increased circulating IL-17A levels, suggesting that this cytokine can be involved in the onset of hypertension and hypertension related end-organ damage." (PMID 31963845, 2020). "Interestingly, studies in murine models of hypertension identified γδ T lymphocytes as the main source of IL-17A in hypertrophic hearts, kidneys, and aorta." (PMID 32987705, 2020). "Moreover, IL-17A contributed to aortic stiffening and to vascular fibrosis —processes that are relevant in vascular dysfunction and a characteristic feature of arterial hypertension." (PMID 31396305, 2019). "The dose chosen in our study is expected to provide IL-17A exposure in the range described in pre-hypertensive patients and suggests that low circulating IL-17A levels could be involved in the generation of hypertension." (PMID 31572188, 2019).
Hypertension (continued). "Besides traditional risk factors and the effect of ART on blood pressure, IL-17A, IFN-γ, and CD4+ T cells were among the inflammatory parameters associated with hypertension in ART treated PLWH [13••, 56]." (PMID 31165257, 2019). "RhoA/Rho-kinase and NO regulation contribute to IL-17A-mediated hypertension." (PMID 31572188, 2019). "Indeed, IL-17A-expressing cells were observed in target tissues of hypertension-induced damage, including the cardiovascular system and the kidneys, as observed here in experimental hypertension in rats." (PMID 31572188, 2019). "Since IL-17A is linked to Ang II induced HTN, renal dysfunction, and renal sodium transporter modulators, studies suggest that antibodies directed against IL-17A or the IL-17RA receptor subunit may be a novel adjunct hypertension therapy." (PMID 31186952, 2019). "Moreover, IL-17A promotes excessive and sustained RSNA by acting on the CNS, which suggests that a brain–kidney interaction may explain the pathogenesis of IL-17A-induced hypertension." (PMID 40028265, 2025). "Chronic elevated circulating levels of IL-17A could contribute to organ damage and hypertension." (PMID 40028265, 2025). "In addition, utilizing animal models of hypertension, others have reported antagonism (genetic knockdown or neutralizing antibodies) of IL-17A reduced blood pressure and the incidence of target organ damage by acting on the vascular wall and tubular sodium transport." (PMID 38791032, 2024). "Even though these two cytokines share the strongest sequence homology and both modulate pro-inflammatory responses, IL-17A, but not IL-17F, has been demonstrated to play a role in hypertension-associated end-organ damages for cardiac, vascular, and renal injuries." (PMID 36835372, 2023). "Therefore, IL-17A may regulate the inflammatory response, leading to the accumulation of multiple immune cell subpopulations in hypertension." (PMID 35676631, 2022). "Moreover, IL-17A also promotes endothelial dysfunction and angiotensin II-induced hypertension." (PMID 36012327, 2022). "Additionally, BBB dysfunction is found in some pathological conditions such as heart failure and hypertension, so that IL-17A in the periphery may more readily penetrate the BBB to reach the brain." (PMID 36312009, 2022). "However, experimental data have shown that overexpression of IL-17A in keratinocytes of the murine model [K14-IL-17A (ind/+)] induced systemic vascular inflammation, arterial hypertension, and endothelial dysfunction, all of which can lead to an increased risk of CVDs." (PMID 34803716, 2021). "However, the kidney effects of IL-17A in the context of hypertension remain to be investigated." (PMID 31572188, 2019). "Within hypertension, these γδ T cells as well as CD4+ T cells function by aiding in the activation of CD8+ T cells or through cytokine production, including IFNγ and IL-17A." (PMID 36970367, 2023). "An experiment showed that lactulose supplementation in high salt diet (HSD)-fed mice increases the abundances of Bifidobacterium, Alloprevotella and Subdoligranulum by decreasing the IL-17a and IL-22 mRNA, leading to the relief of HSD-induced hypertension." (PMID 36195874, 2022). "The unconventional and rather small subgroup of γδ T cells has receptors composed of γ- and δ-chains and plays a role in hypertension by producing IL-17A and IFN-γ (for further elaboration of the hypertensive effects of IL-17A and IFN-y, see CD4+ T cells)." (PMID 35354938, 2022). "In the context of inflammation in hypertension, indoles can inhibit TH17 cells and suppress the release of IL-17A, thus reducing sodium retention." (PMID 34485420, 2021). "In this experiment, the transfer of Th17 cells enhances the proportion of CD4+IL-17A+ (Th17) cells in the PBMCs and the spleen of recipient SHR by which hypertension consequently develops." (PMID 33688497, 2021).
Hypertension (continued). "The presence of IL-17A-expressing cells in the kidneys of patients with hypertensive nephroesclerosis supports the clinical translation of our experimental findings and suggests that IL-17A blockade could be considered as a potential approach to prevent hypertension-induced kidney inflammation." (PMID 31572188, 2019). "During a murine N(omega)-nitro-L-arginine methyl ester hydrochloride (L-NAME)/high-salt model of hypertension, T(EM) accumulated in the kidney and produced IFN-γ and IL-17A." (PMID 31321561, 2019). "Our data confirm and extend previous studies showing that IL-17A targeting decreased kidney inflammation in preclinical models of renal damage, suggesting that the blockade of IL-17A could be an anti-inflammatory treatment to prevent hypertension-induced renal inflammation." (PMID 31572188, 2019). "Indeed, previous studies showed that innate and adaptive immunity participate to cardiovascular diseases and hypertension by the production of pro-inflammatory cytokines such as TNF-alpha, IFN-gamma and IL-17A." (PMID 40303366, 2025). "In angiotensin II-infused mice, serum levels of IL-17A, IL-23, and TNF-α, which have roles in maintaining hypertension, were shown to be significantly increased, while serum levels of the anti-inflammatory factor IL-10, which has cardiovascular protective effects, were significantly decreased." (PMID 40028265, 2025). "The CD4+ T helper 17 (TH17) axis plays a significant role in regulating the immune system in SSH by influencing the activity of TH17 cells and the expression of Interleukin 17A (IL-17) through key factors like SGK1 and NFAT5, potentially contributing to the development of diseases like hypertension." (PMID 39091359, 2024). "Moderate positive correlations of the T2 with IL-7 (ρ = 0.455; p = 0.033), IL-10 (ρ = 0.578; p = 0.005), IL-12P40 (ρ = 0.500; p = 0.018), and IL-17A (ρ = 0.452; p = 0.035) levels were observed only in patients without hypertension." (PMID 39685774, 2024). "Studies demonstrated that mice lacking IL-17A are protected from hypertension and vascular dysfunction in response to ANG II." (PMID 38673987, 2024). "An absence of IL-17A increase in the brain was also observed in a high-salt diet model of hypertension despite an increase in the circulating IL-17A." (PMID 36835372, 2023). "Mice lacking IL-17A develop blunted hypertension and do not develop endothelial dysfunction in response to Ang II infusion." (PMID 35360231, 2022). "Consistent with this, the increased production of vascular superoxide during hypertension does not normally occur in mice lacking IL-17A." (PMID 35676631, 2022). "Proinflammatory cytokines like IL-17A and IFN-γ can induce hypertension by altering the reabsorption of sodium through its transporters: sodium-hydrogen exchanger-3 (NHE3), sodium-potassium-chloride cotransporter (NKCC) and sodium-chloride cotransporter (NCC) on the renal tubules." (PMID 35770194, 2022). "Despite the absence of an increase in the proportion of CD4+FoxP3+ (Treg) cells in the recipient WKY, the increased proportion of CD4+IL-17A+ (Th17) cells did not affect the onset of hypertension." (PMID 33688497, 2021). "The transfer of Th17 cells isolated from adult donor SHR blood significantly increases the proportion of CD4+IL-17A+ (Th17) cells in the PBMCs and the spleen of recipient juvenile rats and induces early hypertension in the juvenile recipient SHR." (PMID 33688497, 2021). "Prior research suggests that dysbiotic gut microbiome could promote TH17 cell activation and stimulate the release of IL-6, IL-17A, and IFN-γ, leading to hypertension." (PMID 34573025, 2021). "Hypertension is not sustained in IL-17A-/- mice infused with Ang II." (PMID 35371030, 2022).
Hypertension (continued). "From the results, CD4+IL-17A+ (Th17) cells isolated from SS rats maintained on 20% fructose solution induced hypertension in recipient SS but not SR rats, whereas CD4+IL-17A+ (Th17) cells isolated from SS rats maintained on tap water did not affect blood pressure in either recipient group." (PMID 32179549, 2020). "IL-17A–producing CD4+ T cells and γδ T cells are an important source of inflammation in hypertension and recognize IsoLG-adducted peptides in mouse models of nonischemic heart failure." (PMID 39145457, 2024).
liver fibrosis (191 papers, 2012 to 2026). "Patients with the dominant genotype (GA + AA) of the IL17A-G197A polymorphism exhibited 3.91 times greater odds of experiencing at least a one-stage increase in liver fibrosis compared to those with the GG genotype (adjusted OR = 3.91, 95% CI: 1.33–12.34)." (PMID 40332363, 2025). "In the multivariable ordinal logistic regression, the IL17A-G197A polymorphism remained significantly associated with higher liver fibrosis stages (adjusted p = 0.0155)." (PMID 40332363, 2025). "A higher stage of liver fibrosis was significantly associated with the dominant genotype of the IL17A-G197A gene polymorphism (p = 0.0004)." (PMID 40332363, 2025). "Plasma IL-10/IL-17A ratio was associated with the histological advancement of liver fibrosis (Kruskal-Wallis, p=0.028)." (PMID 40918132, 2025). "Patients with the dominant genotype (GA + AA) of the IL17A-G197A gene polymorphism had 3.91-fold higher odds of experiencing at least a one-stage increase in liver fibrosis compared to those with the GG genotype (adjusted OR = 3.91, 95% CI: 1.33–12.34)." (PMID 40332363, 2025). "IL-17 deficiency (Il17a-/-) in the MCD-induced models was shown to reduce liver fibrosis, while treating the HFD-induced MASH model with recombinant IL-17 worsened fibrosis development." (PMID 39156888, 2024). "All of these results are in correlation with the results of our study and demonstrate a strong association of IL-17A with chronic hepatitis-induced liver fibrosis, but more preclinical and patients cohort studies are needed to confirm this link." (PMID 37569857, 2023). "The pathogenic role of IL-17A has been demonstrated in different etiological causes of liver fibrosis in animal models." (PMID 36077175, 2022). "IL-17A and IL-17RA deficient mice demonstrate reduced liver fibrosis, suggesting a pro-fibrotic role of IL-17." (PMID 34064375, 2021). "japonicum infection, Vγ2 T cells can recruit neutrophils and aggravate liver fibrosis by secreting IL-17A, thereby causing the eggs to be trapped." (PMID 30992086, 2019). "The results from the study by Tan showed increased IL-17A expression in patients with hepatic fibrosis caused by hepatitis B virus, which indicated that IL-17A plays an important role in the progression of liver fibrosis." (PMID 31639000, 2019). "Although IL-17A was implicated in promoting liver fibrosis by inducing HSCs activation, we only observed a slight decrease in the degree of fibrosis during IL-17A blockade in CCl4-induced fibrosis." (PMID 30930903, 2019). "Toll-like receptor-3 deficiency in HSCs contributed to decreased IL-17A production by γδ T cells, as well as liver fibrosis." (PMID 27824548, 2016). "caused liver fibrosis whereas IL-17A can promote the activation of HSC and drive the mRNA expression of the IL-6, α-SMA, collagen, as well as TGF-β1 in carbon tetrachloride–induced liver fibrosis." (PMID 25649869, 2015). "Patients possessing the dominant genotype (GA + AA) of the IL17A-G197A gene polymorphism have a risk 3.91 times greater of developing at least a one-stage increase in liver fibrosis than individuals with the GG genotype (adjusted OR = 3.91, 95% CI: 1.33–12.34)." (PMID 40332363, 2025). "IL-17A plays a key role in the inflammatory pathways associated with liver injury and may serve as a potential adjunctive diagnostic marker for liver fibrosis." (PMID 39995661, 2025). "Similarly, polymorphisms of the IL17 gene, particularly those affecting IL-17A and IL-17F, can influence the production of IL-17, a cytokine vital for mediating inflammation and liver fibrosis." (PMID 40332363, 2025). "Retinoic acid may also regulate the expression of IL-17A, a vital inflammatory factor associated with liver fibrosis." (PMID 40299397, 2025).